KDM6A (lysine demethylase 6A)
Diseases named in the same sentence as KDM6A in open-access papers (continued):
Sharing a sentence is not in itself a finding about the gene and the disease.
pancreatic cancer (continued). "Carcinomas: Work with pancreatic cancer (PANCS) supports the concept that KDM6A normally acts as a tumour suppressor, since ablation of KDM6A can lead to development of PANCS in a mouse model, and in patients, oncogenes are activated in females and in males with UTY loss." (PMID 35406676, 2022). "For example, demethylase-independent mechanisms were responsible for KDM6A-mediated regulation of gene expression during mouse embryonic development 11, whereas KDM6A suppressed squamous-like pancreatic cancer growth in male mice similarly independently of its demethylase activity." (PMID 33456567, 2021). "Among those genes, KDM6A was inactivated in 18% of the pancreatic cancer patients." (PMID 27999365, 2016). "However, these factors are not related to the Wnt-independency phenotype in RNF43-mutant pancreatic cancer, since sgRNAs targeting KDM6A or negative regulators of GLI2 or YAP1, i.e., PTCH1, LATS1, and SAV1, were not enriched in ETC-159 versus vehicle-treated tumors in our initial CRISPR screens." (PMID 35536676, 2022). "The chromatin modifier KDM6A, which has been implicated in the progression of squamous PDAC, is a common mutation shared by GSK3b inhibitor-sensitive PDCLs, and in keeping with reported findings, we observe squamous-like pancreatic cancer in these PDCLs despite the presence of GATA6." (PMID 32402285, 2020). "KDM6A demethylase the H3K27, it suppresses pancreatic cancer through maintaining differentiated acinar cell programs and its loss of function induces adeno to squamous plasticity in pancreatic cancer." (PMID 41415713, 2025). "KDM6A and MLL2 were found to be the most frequently altered histone methylation regulatory genes in pancreatic cancer through whole genome sequencing." (PMID 36599884, 2023). "KDM6A in EMT: KDM6A, also known as UTX, specifically catalyzes the demethylation of H3K27me3 and is downregulated in pancreatic cancer cells." (PMID 36902253, 2023). "According to further studies, KDM6A contributes to differentiation, normal growth, cell migration and invasion, and tumor suppression independent of its demethylase activity in pancreatic cancer cells." (PMID 38791111, 2024). "Hence this study suggests that KDM6A and UTY have tumor-suppressive roles in pancreatic cancer and that sex-specific mechanism should be investigated in melanoma and other cancers." (PMID 34220955, 2021). "PTEN, KDM6A, and ARID1A are not established targets for successful drugs, and their evident loss of function in PDAC does not provide therapeutic strategies that are well-validated in pancreatic cancer patients." (PMID 40723241, 2025). "In addition, male mice that expressed UTY and female mice with heterozygous KDM6A expression exhibited a less aggressive pancreatic cancer phenotype, while male and female mice with no UTY or KDM6A exhibited a more aggressive malignant phenotype." (PMID 34220955, 2021).
multiple myeloma (25 papers, 2017 to 2024). "For example, acute myeloid leukemia and multiple myeloma cell lines with KDM6A mutations are more sensitive to EZH2 inhibitors than KDM6A wild-type expressing lines." (PMID 35137163, 2022). "Regarding clinical actionability, in multiple myeloma, KDM6A mutations accounted for 10% of 58 patients." (PMID 36052737, 2022). "Disruptive KDM6A mutations were found in lymphoid neoplasms such as multiple myeloma and T-cell acute lymphoblastic leukemia." (PMID 35454811, 2022). "Loss of KDM6A expression has also been associated with other cancers such as multiple myeloma (MM) in which KDM6A mutations lead to low KDM6A expression, resulting in increased proliferation, adhesion and tumorigenicity." (PMID 34220955, 2021). "Reduced expression or mutations/deletions of KDM6A correlate with poor overall survival in patients with CN-AML or myeloma, respectively." (PMID 31201358, 2020). "Disruptive KDM6A mutations have been found in multiple myeloma, bladder neoplasms and T cell acute lymphoblastic leukemia (T-ALL)." (PMID 29989027, 2018). "Work by others also recently showed that KDM6A knockout can lead to CD38 transcript downregulation in myeloma models." (PMID 40453054, 2024). "Accordingly, rebalancing of H3K27me3 levels at specific genes through EZH2 inhibitors has been proposed as a therapeutic strategy in cases of multiple myeloma and urothelial bladder carcinomas harboring KDM6A/UTX mutations." (PMID 34153035, 2021). "These include mutations in the H3K27me3 demethylase KDM6A (also known as UTX), where loss of KDM6A function results in increased proliferation, adhesion, and clonogenicity of myeloma cells." (PMID 31231360, 2019). "UTX/KDM6A, a histone H3K27 demethylase and a key component of the COMPASS complex, is frequently lost or mutated in cancer; however, its tumor suppressor function remains largely uncharacterized in multiple myeloma (MM)." (PMID 37198323, 2023). "In support of our data, neuroblastoma is the third most sensitive among 25 different cancer lineages that are sensitive to knockdown of KDM6B but not KDM6A, just below prostate cancer and myeloma, in a genome-wide shRNA screen (20 shRNAs per gene) in 709 cancer cell lines (DepMap dataset)." (PMID 34893606, 2021).
acute myeloid leukemia (22 papers, 2016 to 2026). Acute myeloid leukemia (AML) is a group of neoplasms arising from precursor cells committed to the myeloid cell-line differentiation. "Background/Objectives: The role of KDM6A gene mutations in acute myeloid leukemia (AML) remains poorly understood." (PMID 40647534, 2025). "Variants of KDM6A result in global epigenetic dysregulation and are associated with diverse cancers, including acute myeloid leukemia (AML)." (PMID 40647534, 2025). "KDM6A mutations are found in a variety of human cancers, including multiple myeloma, renal cell carcinoma, bladder carcinoma, acute myeloid leukemia (AML), acute lymphoid leukemia (ALL), prostate cancer, and medulloblastoma." (PMID 30963999, 2019). "Studies have shown that abnormal levels of the histone demethylases lysine demethylase 6A (KDM6A) and KDM6B are associated with pediatric acute myeloid leukemia (AML)." (PMID 36081552, 2022). "Conversely, some KDMs including KDM6A have been shown to be upregulated in human primary acute myelogenous leukemia (AML) cells and inhibiting histone demethylase activity in these cells reduces their survival." (PMID 33456567, 2021). "KDM6A is most frequently mutated in myelodysplastic syndrome (MDS) and acute myeloid leukemia (AML)." (PMID 31238554, 2019). "UTX (also known as KDM6A), a histone 3 lysine 27 demethylase, is among the most frequently mutated epigenetic regulators in myelodysplastic syndrome (MDS) and acute myeloid leukemia (AML)." (PMID 31044091, 2019). "Studies have shown that abnormal levels of the histone demethylases, KDM6A and KDM6B, are associated with pediatric acute myeloid leukemia (AML)." (PMID 34765551, 2021). "A previous study demonstrated that KDM6A promoted a dedicator of cytokinesis (DOCK) 5/8 transcription and Rac GTPase activation to promote tumour metastasis in acute myeloid leukaemia." (PMID 34006303, 2021). "Some studies confirm the frequent co-occurrence of KDM6A and KDM6C, and identify KDM6C as a demethylase independent tumor suppressor in acute myeloid leukemia and squamous-like pancreatic carcinoma." (PMID 34950587, 2021).
acute lymphoblastic leukemia (17 papers, 2016 to 2022). Leukemia with an acute onset, characterized by the presence of lymphoblasts in the bone marrow and the peripheral blood. "KDM6A mutations also occur in acute lymphoblastic leukemia (ALL), and in chronic myelomonocytic leukemia (CMML)." (PMID 34780480, 2021). "In the context of cancer, a study showed that KDM6A had a gender-specific, tumor suppressive effect in T-cell acute lymphoblastic leukemia (T-ALL)." (PMID 34220955, 2021). "In T-cell acute lymphoblastic leukemia (T-ALL), KDM6A mutations are located almost exclusively in the JmjC domain and inactivation of the single KDM6A copy in males is sufficient to contribute to T-ALL pathogenesis." (PMID 31201358, 2020). "A recent study demonstrated that KDM6A is a co-activator of the oncogenic transcription factor TAL1 and is essential for disease progression of TAL1-positive T-cell acute lymphoblastic leukemia (T-ALL)." (PMID 28717873, 2018).
leukemia (16 papers, 2016 to 2024). A malignant (clonal) hematologic disorder, involving hematopoietic stem cells and characterized by the presence of primitive or atypical myeloid or lymphoid cells in the bone marrow and the blood. "Using diagnosis and relapse samples from AML patients, patient-derived xenografts (PDX), and leukemia cell lines, we investigated the status of KDM6A during disease progression and the impact of KDM6A loss on chemotherapy resistance." (PMID 31201358, 2020). "Myb integrations and Kdm6a mutations were observed in three and two independent leukemias, respectively." (PMID 31199785, 2019). "KDM6A is frequently targeted by somatic loss-of-function mutations in cancer including leukemia." (PMID 31201358, 2020). "Kdm6b loss in mice has been shown to impair HSC self-renewal and enhance HSC differentiation, and Kdm6a-deficient mice have been shown to exhibit abnormal differentiation with myeloid skewing, impaired hematopoietic reconstituting ability, and increased susceptibility to leukemia." (PMID 37917239, 2024). "To identify the frequency of KDM6A deletions in leukemia, we performed MLPA analysis for the KDM6A gene in 40 myeloid leukemia cell lines." (PMID 31201358, 2020). "Indeed, this phenomenon was previously observed in leukaemias, where KDM6A acts as a gender-specific tumour suppressor." (PMID 34509979, 2022). "Recent studies have shown that the KDM6A/UTX, which is responsible for demethylating H3K27me3, have cases of inactivating lesions and downregulation of this gene accelerates NOTCH1-driven leukemia in mice." (PMID 29034206, 2017). "Kdm6a conditional KO mice did not develop spontaneous leukemias, or have an increased incidence of other cancers compared to control mice." (PMID 34780480, 2021).
developmental delay (15 papers, 2012 to 2025). "Haploinsufficiency of KDM6A is similarly associated with more severe psychomotor developmental delays." (PMID 36292647, 2022). "For example, haploinsufficiency of KDM6A in humans causes severe psychomotor developmental delay, global growth restriction, seizures and cleft palate." (PMID 35212626, 2022). "Variants in both KMT2D and KDM6A lead to improper cell differentiation, ultimately causing a characteristic dysmorphism and developmental delay." (PMID 33805950, 2021). "A fluorescence in situ hybridization and Whole Genome Sequencing study was performed, analyzing a female KS patient with a known KDM6A variant and a phenotype including hypotonia, developmental delay, short stature, microcephaly, seizures, facial dysmorphism and cleft palate." (PMID 33805950, 2021). "In our cohort, several genes were frequently implicated in cases of genetic epilepsy and developmental delay, including PRRT2 (n:2), KCNQ2 (n:2), SCN1A (n:2), PLA2G6 (n:2), and KDM6A (n:2)." (PMID 40083435, 2025). "The current diagnosis relies mainly on the identification of infantile hypotonia, developmental delay, or intellectual disability, combined with typical dysmorphic features and KMT2D or KDM6A mutations based on genetic testing." (PMID 38115267, 2023).
lung cancer (15 papers, 2018 to 2025). A malignant neoplasm involving the lung. "It is also reported that KDM6A is often mutated which shows different manifestations in different cancer types such as medulloblastoma, colon, non–small cell lung cancer, pancreas, bladder, urinary tract, esophagus, and HCC." (PMID 41244070, 2025). "KDM6A, frequently mutated in bladder and lung cancers, has been associated with lineage flexibility and aggressive basal-like phenotypes in PDAC." (PMID 41303383, 2025). "The present results also suggested that EZH2 inhibitors might have a role in the treatment of melanoma that expresses high EZH2 and low KDM6A as loss of KDM6A sensitizes bladder and lung cancer cells to treatment with EZH2 inhibitors." (PMID 32731355, 2020). "Conversely, KDM6A has an oncogenic role in acute myeloid leukemia and non–small cell lung cancer." (PMID 41244070, 2025). "Lung tumors with KDM6A loss was more sensitive to EZH2 inhibition, indicating lung cancer patients with specific histone methylation features might benefit from specific epigenetic therapy." (PMID 30002791, 2018). "However, a recent study unveiled KDM6A as an important tumor suppressor gene in lung cancer with evidence gained from human lung cancer specimens and transgenic NSCLC mouse models." (PMID 30002791, 2018). "Lysine Demethylase 6A (KDM6A) expression was not correlated with poor survival in lung cancer patients." (PMID 36233212, 2022). "This balance between KDM6A and EZH2 may be important in guiding therapeutic strategy in multiple diseases, including lung cancer." (PMID 30002791, 2018).
medulloblastoma (14 papers, 2013 to 2024). A malignant, invasive embryonal neoplasm arising from the cerebellum. "Surprisingly, mutations in H3K27me2/3 demethylase Lysine Demethylase 6A (KDM6A) are common in medulloblastoma." (PMID 37107631, 2023). "Intermediate expression for EZH2 and H3K27me3 was found for SHH medulloblastoma samples, with both low and high expression of KDM6A and KDM6B." (PMID 29108280, 2017). "The histone methylases EZH2 and KDM6A represent possible future targets of these subgroups as they appear to be exclusively expressed in groups 3 and 4 medulloblastomas." (PMID 25101241, 2014). "The H3K27me3 demethylase KDM6A was reported to have a tumor suppressor function in medulloblastoma." (PMID 33681213, 2021). "Approximately 15% of Group 4 medulloblastomas displayed mutations of KDM6A: these mutations were observed only in this group, more rarely in Group 3, but not in other medulloblastoma groups." (PMID 30279357, 2018). "Interestingly, chromosome X loss is seen in 80% of females with group 4 medulloblastomas Groups 3 and 4 medulloblastomas have recently been shown to have EZH2 and KDM6A alterations which are involved in histone methylation (specifically H3K27)." (PMID 25101241, 2014). "We identified two point mutations in KDM6A, which had not previously been identified in medulloblastomas, and validated germline mutations in BRCA2, RAD51D and ATM, which are all involved in DNA repair of double-stranded breaks as well as hereditary cancer syndromes." (PMID 37576901, 2023). "In medulloblastoma, the demethylase UTX/KDM6A can promote the secretion of the th1-type chemokine CXCL9/CXCL10 via H3K27me3 demethylation, thereby facilitating the recruitment of CD8+ T cells into the TME." (PMID 39080807, 2024).
urothelial carcinoma (13 papers, 2019 to 2025). A malignant neoplasm derived from the transitional epithelium of the urinary tract (urinary bladder, ureter, urethra, or renal pelvis). "We also investigate the gender-biased differential effect of KDM6A mutation in several public databases of urothelial carcinoma (UC)." (PMID 39941725, 2025). "The highest frequency of KDM6A mutations was found in 26% of all urothelial carcinomas, 52% of which were superficial and 38% were muscle-invasive urothelial carcinomas." (PMID 39118085, 2024). "KDM6A is frequently affected by deleterious mutations in urothelial carcinoma (UC) and other cancers." (PMID 32326336, 2020). "Deleterious mutations in KDM6A occur in many human cancers, most frequently in urothelial carcinoma." (PMID 32326336, 2020). "Among all cancer types, deleterious KDM6A mutations are most frequent in urothelial carcinoma (UC), the most common histological type of urinary bladder cancer." (PMID 30987376, 2019). "Additionally, a case of PRNRP with KRAS mutation was also reported synchronously with urothelial carcinoma with a distinct FGFR3/KDM6A mutation." (PMID 40860802, 2025). "Loss of the X-linked histone demethylase lysine demethylase 6A (KDM6A), an H3K27 demethylase, occurs in a large fraction of urothelial carcinomas." (PMID 41322853, 2025). "Here, we show that introduction of functional UTX/KDM6A has quite diverse effects in urothelial carcinoma cell lines representing a broad spectrum of genotypes and phenotypes that reflect the heterogeneity of this cancer type." (PMID 30987376, 2019). "The histone demethylase Ubiquitously Transcribed Tetratricopeptide Repeat Protein X-Linked (UTX/KDM6A) demethylates H3K27me2/3 at genes and enhancers and is often inactivated by mutations in urothelial carcinoma (UC)." (PMID 30987376, 2019).